NNMT (nicotinamide N-methyltransferase)
Diseases named in the same sentence as NNMT in open-access papers (continued):
Sharing a sentence is not in itself a finding about the gene and the disease.
breast carcinoma (continued). "However, we believe that other unknown factors may also participate in neddylation pathway activation in breast cancer, because NEDD8‐activating enzyme E1(NAE1), whose expression wasn't regulated by NNMT, was also reported to be highly expressed in breast cancer tissue compared with ANT." (PMID 38126621, 2024). "In separate studies, GPX8-KO suppressed IL6-STAT3 pathway in breast cancer cells, and IL6-STAT3 was shown to regulate NNMT expression." (PMID 36750850, 2023). "NNMT overexpression increases the chemoresistance through SIRT1 stabilization and activity in breast cancer." (PMID 36817086, 2023). "On the contrary, overexpression of NNMT in the MCF-7 and SK-BR-3 breast cancer cell lines showed attenuated apoptosis when compared to negative control cells." (PMID 24558488, 2014). "In vivo experiments show that NNMT-knockdown, NNMT inhibitors and FAO inhibitors can all reduce lung metastases formation, suggesting that targeting NNMT-FAO suppresses the metastatic potential of breast cancer." (PMID 41816955, 2026). "Notably, during the developmental trajectory of cells, breast cancer stem cells (BCSCs) tend to express genes such as IER3 and GADD45B at the early stage, while genes like NNMT and LDHB are preferentially expressed in the BCSCs-2 developmental state." (PMID 40092692, 2025). "Although there are no reports in ovarian cancer, one study showed that NNMT expression in breast cancer tumor cells enhances chemotherapy resistance." (PMID 40853419, 2025). "The LC3B II level was reduced by 50% in SK-BR-3-NNMTOEx cells compared to that in SK-BR-3-Vector cells with or without BafA1, which suggests that NNMT overexpression decreased autophagy flux in breast cancer cells." (PMID 32489327, 2020). "We suppose that the production of ROS and condition of PP2A methylation and demethylation regulated by NNMT may contribute to the phosphorylates ERK and AKT in breast cancer, however, this needs more detailed experiments to confirm." (PMID 24558488, 2014). "We don’t know the exact mechanisms of How NNMT phosphorylates ERK and AKT in breast cancer so far." (PMID 24558488, 2014). "However, the functional role of NNMT in breast cancer has not been elucidated." (PMID 24558488, 2014). "However, the mechanism of NNMT in cell proliferation is largely unknown and the functional role of NNMT in breast cancer has not been reported." (PMID 24558488, 2014). "Converse results were obtained after NNMT upregulation in MCF-7 and SK-BR-3 breast cancer cell lines that lacked constitutive NNMT expression." (PMID 38504052, 2024). "In breast cancer (BRCA) and 16 other cancer types NNMT had a strong negative relationship to mRNA methyltransferases." (PMID 37883365, 2023).
ovarian carcinoma (30 papers, 2017 to 2026). A malignant neoplasm originating from the surface ovarian epithelium. "Our own work recently identified a stromal signature of ovarian cancer metastasis and identified nicotinamide N-methyltransferase (NNMT) as a promising new drug target against cancer-associated fibroblasts." (PMID 41233595, 2026). "This signature features known disease drivers and oncogenic ECM proteins associated with ovarian cancer progression and metastasis (e.g., NNMT, CD163, and FN1) and sheds light on proteins with high therapeutic potential." (PMID 41233595, 2026). "While NNMT inhibition reprograms immunosuppressive niches in ovarian cancer, its immunomodulatory effects on HCC-associated macrophages or stromal compartments remain unexplored." (PMID 40427612, 2025). "Its role in directly regulating the SAM:SAH ratio in cells implicates NNMT in playing a significant role in controlling the gene expression within ovarian cancer cells and cancer-associated fibroblasts (CAFs)." (PMID 39272943, 2024). "Recent evidence suggests that in ovarian cancer, NNMT expression is associated positively with PGAM1, which is involved in the Warburg effect, enabling the elucidation of the resistance mechanism of bevacizumab." (PMID 35756670, 2022). "In conclusion, NNMT expression is associated with the aggressive behavior of ovarian cancer, correlates with a poor prognosis, and is predictive of sensitivity to bevacizumab treatment." (PMID 33446144, 2021). "Our aim is to explore the expression of NNMT in ovarian cancer and to assess its association with patient prognosis and treatment response." (PMID 33446144, 2021). "Notably, PRDX6 overexpression is associated with higher NNMT protein levels in human ovarian cancer tissues and is predictive of poor prognosis of ovarian cancer patients." (PMID 39887931, 2025). "NNMT expression in ovarian cancer cells is associated with poor prognosis." (PMID 40853419, 2025). "In addition, NNMT depletion in parental ovarian cancer cell lines with high baseline NNMT expression, such as SKOV3 and OVCAR4, caused a drastic decrease in their viability in low glucose conditions." (PMID 28412735, 2017). "Similarly, NNMT KD could also rescue the enhanced ovarian cancer growth and metastasis caused by PRDX6‐MUT overexpression in both subcutaneous and peritoneal metastatic xenograft mice models, respectively." (PMID 39887931, 2025). "Collectively, these data demonstrate that PRDX6 stabilizes and upregulates NNMT protein levels by inhibiting its ubiquitin‐mediated degradation in ovarian cancer cells." (PMID 39887931, 2025). "Collectively, these results indicate that PRDX6‐mediated NNMT upregulation promotes the growth and metastasis of ovarian cancer cells by activating MAPK signaling." (PMID 39887931, 2025). "Our study showed that PRDX6 interacts with NNMT to diminish its proteasomal degradation, leading to the upregulation of NNMT in ovarian cancer." (PMID 39887931, 2025). "Overall, these results indicate that PRDX6 prevents NNMT ubiquitination at lysine 23 and 210, leading to the inhibition of proteasomal degradation and upregulation of NNMT in ovarian cancer cells." (PMID 39887931, 2025). "Together, these results suggest that PRDX6 promotes the growth and metastasis of ovarian cancer cells by upregulating NNMT in vitro." (PMID 39887931, 2025). "Overall, these findings suggest that PRDX6 promotes the growth and metastasis of ovarian cancer cells in vivo by upregulating NNMT." (PMID 39887931, 2025). "Consistently, PRDX6 KO‐mediated suppression of migration and invasion of ovarian cancer cells were markedly rescued by overexpressing NNMT‐K23R/K210R mutant." (PMID 39887931, 2025). "In support of this observation, immunoblotting analysis revealed an obvious decrease in NNMT protein level upon PRDX6 KO or knockdown (KD) by siRNA in ovarian cancer cells." (PMID 39887931, 2025).
ovarian carcinoma (continued). "PRDX6‐mediated NNMT upregulation thus promotes the growth and metastasis of ovarian cancer cells by activating the mitogen‐activated protein kinase (MAPK) pathway." (PMID 39887931, 2025). "In ovarian cancer, the stromal expression of the NNMT protein was found to be correlated with metastasis." (PMID 39858465, 2025). "Taken together, these data indicate that PRDX6‐mediated NNMT upregulation can be potential biomarkers to predict the prognosis of ovarian cancer patients." (PMID 39887931, 2025). "Together, these data suggest that PRDX6 competitively interacts with NNMT to prevent TRIM56‐mediated NNMT ubiquitination, leading to NNMT upregulation in ovarian cancer cells." (PMID 39887931, 2025). "We next interrogated the clinical relevance of PRDX6‐mediated NNMT upregulation in ovarian cancer using a tissue microarray containing 147 cases of human ovarian cancer." (PMID 39887931, 2025). "Here, it is shown that the 1‐cysteine PRDX (PRDX6) upregulates nicotinamide N‐methyltransferase (NNMT) to promote the growth and metastasis of ovarian cancer cells, independently of PRDX6's enzymatic activities." (PMID 39887931, 2025). "NNMT was proved to be indispensable for the pro-tumoral traits of CAFs, as silencing NNMT in CAFs curbed ovarian cancer cell invasion and metastasis in vivo." (PMID 39858465, 2025). "Through proteomic analysis, NNMT has been identified as a key regulator in ovarian cancer proliferation and metastasis, as well as changes in tumor stroma gene expression within CAFs." (PMID 39272943, 2024). "High NNMT expression in glucose-restricted ovarian cancer cells enables metabolic adaptations by utilizing alternative sugars and methylated substrates." (PMID 39272943, 2024). "The loss of S-adenosyl methionine-mediated histone hypomethylation caused nicotinamide N-methyltransferase (NNMT) production in CAFs to enhance cytokine secretion and ECM deposition in ovarian cancer." (PMID 37784082, 2023). "Overexpression of NNMT in the stroma promotes the progression and metastasis of ovarian cancer and interferes with the prognosis of patients." (PMID 35884600, 2022). "Proteomic analysis revealed that NNMT played an indispensable role in for the functional integrity of cancer associated fibroblasts (CAFs), which indicated the importance role of NNMT in regulating the stromal crosstalk in ovarian cancer." (PMID 36313638, 2022). "It has been demonstrated that BRCA1 deficiency drives metabolic reprogramming by upregulating nicotinamide N-methyltransferase (NNMT), sensitizing ovarian cancer cells to agents that inhibit energy metabolism." (PMID 36230683, 2022). "Expression of NNMT on ovarian cancer cells supported migration, proliferation, growth, and metastasis in vivo." (PMID 36186458, 2022). "Regarding NNMT inhibition in cancer, one study showed decreased tumour burden and cancer cell proliferation in an orthotropic mouse model of ovarian cancer treated with an NNMT inhibitor." (PMID 35678045, 2022). "Owing to high NNMT expression, glucose-restricted ovarian cancer cells can acquire metabolic adaptations, using other sugars and some methylated substrates to feed their metabolism." (PMID 35756670, 2022). "A recent proteomics-based study has revealed that NNMT is a main metabolic regulator of CAFs in ovary cancer." (PMID 35756670, 2022). "It has recently been reported that BRCA1 DNA repair associated (BRCA1) deficiency, in ovarian cancer cells, upregulates NNMT expression, as BRCA1 binding to a NNMT promoter negatively regulates NNMT transcription." (PMID 34073600, 2021). "Our data also demonstrated that NNMT expression was positively correlated with PGAM1 expression in ovarian cancer." (PMID 33446144, 2021). "Consistently, our results also indicated that NNMT expression was increased in mesenchymal molecular subtype of ovarian cancer compared with other molecular subtypes of ovarian cancer." (PMID 33446144, 2021).
ovarian carcinoma (continued). "In contrast, KD of NNMT in ovarian carcinoma cells had the opposite effect as it increased the SAM/SAH ratio, as well as global H3K9 and H3K27 trimethylation." (PMID 31294922, 2019). "Our studies define a novel ZEB1/NNMT signaling axis, which elicits mesenchymal gene expression, as well as phenotypic and metabolic plasticity in ovarian cancer cells upon chronic glucose starvation." (PMID 28412735, 2017). "Taken together, these in silico results prompted us to assess NNMT protein expression in primary, metastatic and recurrent ovarian carcinomas." (PMID 28412735, 2017). "In summary, our results suggest that the ZEB1/NNMT signaling axis induces phenotypic and metabolic plasticity, as well as mesenchymal gene expression in ovarian cancer cells upon chronic glucose deprivation." (PMID 28412735, 2017). "In our panel of ovarian cancer cell lines, NNMT protein expression positively correlated with expression of ZEB1 and other mesenchymal markers, such as vimentin." (PMID 28412735, 2017). "Expression in cancer-associated fibroblasts (CAFs) in highly atypical serous carcinomas in ovarian cancer, NNMT expression in CAFs, has resulted in depletion of S-adenosylmethionine and decreased histone methylation associated with extensive gene expression changes in the tumor stroma." (PMID 40853419, 2025). "NNMT KD significantly decreased the clone numbers, migration, and invasion of ovarian cancer cells." (PMID 39887931, 2025). "Moreover, the ectopic expression of PRDX6 markedly elevated NNMT protein level in ovarian cancer cells." (PMID 39887931, 2025). "We then mutated both lysine 23 and 210 residues of NNMT‐GFP to arginine simultaneously (K23R/K210R), and found the K23R/K210R double mutation of NNMT markedly impeded the reduction of NNMT protein level caused by PRDX6 KO in ovarian cancer cells." (PMID 39887931, 2025). "Notably, nicotinamide N-methyltransferase (NNMT) was found to be upregulated in CAFs within metastatic ovarian cancer lesions, where it depletes S-adenosyl methionine, the principal methyl donor for histone methylation." (PMID 41301911, 2025). "Growing evidence has shown that NNMT is aberrantly expressed in several cancers and is a promising prognostic predictor in cancers such as gastric carcinoma, oral squamous cell carcinoma, ovarian cancer, hepatocellular carcinoma, and nasopharyngeal carcinoma." (PMID 40853419, 2025). "In addition, treatment with the proteasome inhibitor MG132 obviously increased NNMT protein level, and rescued PRDX6 KO‐mediated decrease of NNMT protein level in ovarian cancer cells." (PMID 39887931, 2025). "NNMT has been found to have elevated expression in peritoneal stroma and omental metastases in ovarian cancer, and its expression correlates with the aggressive behavior of ovarian cancers with poor prognosis." (PMID 39272943, 2024). "In addition, CAF-expressed methyltransferase NNMT in tumor stroma can support ovarian cancer proliferation." (PMID 37784082, 2023). "The role of nicotinamide N-methyltransferase (NNMT) in ovarian cancer is still elusive." (PMID 33446144, 2021). "We first analyzed the differential expression of NNMT among fallopian tube epithelium, primary ovarian cancers, metastatic ovarian cancers, and recurrent ovarian cancers using Gene Expression Ominus (GEO) database (GSE10971, GSE30587, GSE44104 and TCGA datasets)." (PMID 33446144, 2021). "Future researches are needed to establish the role of NNMT in ovarian cancer development, and to explore whether combined therapy with NNMT inhibitor and bevacizumab could be translated into survival improvements." (PMID 33446144, 2021). "Our data also show that NNMT expression is highest in the mesenchymal subtype of ovarian cancer." (PMID 28412735, 2017). "Similarly, we used CRISPR/Cas9 to deplete NNMT in SKOV3 ovarian cancer cells (endometrioid/clear cell subtype), a cell line previously shown to have high NNMT activity." (PMID 28412735, 2017).
ovarian carcinoma (continued). "Similarly, NNMT KD could also compromise the tumor‐promoting effect of PRDX6‐MUT in ovarian cancer cells." (PMID 39887931, 2025). "Interestingly, BRCA1 depletion-induced NNMT upregulation was shown to promote metabolic reprogramming of ovarian cancer cells, which sensitized ovarian cancer cells to agents that inhibit mitochondrial metabolism (VLX600 and tigecycline) and to agents that inhibit glucose import (WZB117)." (PMID 33193702, 2020). "We conclude that ectopic ZEB1 expression is sufficient to upregulate NNMT and other mesenchymal genes, enable cells to use methylated substrates as an alternative energy sources, and induce glucose independence in glucose-dependent epithelial ovarian cancer cell lines." (PMID 28412735, 2017). "Our study found that PRDX6‐mediated NNMT upregulation activates MAPK pathway, thereby provoking the proliferation and metastasis of ovarian cancer cells." (PMID 39887931, 2025). "In detail, PRDX6 competitively interacts with NNMT to prevent its binding to the E3 ubiquitin ligase TRIM56, resulting in the inhibition of ubiquitin‐mediated degradation of NNMT to activate MAPK signaling pathway and promote ovarian cancer progression." (PMID 39887931, 2025). "PRDX6 interacts with and upregulates NNMT via preventing TRIM56‐mediated ubiquitination and proteasomal degradation, thereby activating MAPK signaling and promoting ovarian cancer progression." (PMID 39887931, 2025). "NNMT was found to be targeted by FTO, which was upregulated and found to demethylate NNMT transcripts in FTO-overexpressing ovarian cancer cells." (PMID 39272943, 2024). "Still, upstream regulators of NNMT in cancer were shown to be diverse, as in BRCA1 for ovarian cancer, HNF1β for thyroid cancer, and SHH for pancreatic cancer." (PMID 36750850, 2023). "Although these data need further experimental evaluation, it seems likely that, similar to ovarian cancer, 1‐MNA acts as an immune‐suppressive metabolite in ccRCC, suggesting a dual effect of NNMT inhibition in ccRCC." (PMID 35678045, 2022). "NNMT expression in solid tissue of RCC was especially high in comparison with several other cancer tissues, including cervical, lung, liver, and ovarian cancer." (PMID 32992891, 2020). "NNMT was recently found to be an important regulator of CAF activity and tumor progression in the stroma of ovarian cancer." (PMID 31652035, 2019). "Notably, eight proteins upregulated in the invasive stroma (NNMT, FCGR1A, FCER1G, TYMP, F13A1, DCK, CASP3, and SYK) represented FDA-approved drug targets outside of ovarian cancer, emphasizing their high relevance for future preclinical investigations." (PMID 41233595, 2026). "The nonenzymatic mechanism of PRDX6 in promoting ovarian cancer progression underscores the upregulation of NNMT." (PMID 39887931, 2025). "In addition, PRDX6‐mediated NNMT upregulation activates mitogen‐activated protein kinase (MAPK) signaling, thereby promoting the growth and metastasis of ovarian cancer cells." (PMID 39887931, 2025). "Notably, ovarian cancer patients exhibiting high protein levels of both PRDX6 and NNMT showed worse overall and progression‐free survival." (PMID 39887931, 2025). "Compared with parental cells, KO of PRDX6 significantly reduced the half‐life of NNMT protein, whereas ectopic expression of PRDX6 markedly prolonged the half‐life of NNMT protein in ovarian cancer cells, suggesting that PRDX6 enhances the protein stability of NNMT." (PMID 39887931, 2025). "The upregulation of NNMT then alters metabolism and sensitizes ovarian cancer cells to mitochondrial metabolic targeting agents without affecting proliferation." (PMID 39272943, 2024). "Upregulation of NNMT drives the metabolic alteration and sensitizes ovarian cancer cells to mitochondrial metabolic targeting agents without reducing proliferation." (PMID 35756670, 2022).